AQP4 (aquaporin 4)
Diseases named in the same sentence as AQP4 in open-access papers (continued):
Sharing a sentence is not in itself a finding about the gene and the disease.
epilepsy (60 papers, 2007 to 2026). A brain disorder characterized by episodes of abnormally increased neuronal discharge resulting in transient episodes of sensory or motor neurological dysfunction, or psychic dysfunction. "This suggests changes to AQP4 is a common phenotypic change in epilepsy and is likely to be closely associated with altered ionic homeostasis, increasing the propensity for seizures." (PMID 37259148, 2023). "Excessive extracellular potassium is generally accepted to enhance seizure susceptibility, and is a possible implication of Aqp4 in epilepsy due to its critical role in potassium clearance." (PMID 34658792, 2021). "Changes in AQP4 expression are often associated with various diseases such as epilepsy, edema and glioblastoma." (PMID 34006980, 2021). "Recently, it was shown that loss of perivascular AQP4 precedes seizure onset after kainic acid-induced epilepsy in rats, suggesting an involvement in epilepsy etiology." (PMID 33324329, 2020). "The mechanism of epilepsy in pericyte knockout Cdk5 mice may also be linked to decreased polar distribution of AQP4." (PMID 39479522, 2024). "Furthermore, Kir4.1 is co-localized with AQP4 in the astrocyte endfeet and has been implicated in potassium reuptake impairment in AQP4 knockout mice in epilepsy models." (PMID 37762642, 2023). "Interestingly, AQP4 expression is reduced in the kainate model of epilepsy, and this is also confirmed in AQP4 deficit mice in which seizure susceptibility is increased." (PMID 33096746, 2020). "Furthermore, AQP4 knockout animals are also more susceptible to seizures and epilepsy and, in kainate-induced epileptic animal models, a reduction in AQP4 expression was also reported." (PMID 32390802, 2020). "It is difficult to distinguish whether the decrease of perivascular AQP4 channels is a cause or a consequence for epilepsy." (PMID 31798512, 2019). "AQP4 has also been associated with other neurological disorders such as epilepsy." (PMID 26941623, 2016). "Moreover, AQP4 is implicated in the pathogenesis of epilepsy mainly due to its role in regulating extracellular fluid osmolarity and extracellular space (ECS) volume (Schwartzkroin and others 1998)." (PMID 24609207, 2015). "Importantly, partial loss of perivascular AQP4 was also found in hippocampi of epilepsy patients." (PMID 29854942, 2018). "Glymphatic transport depends on astrocytic aquaporin-4 channels and is strongly modulated by sleep-wake state, which is highly relevant to epilepsy given the close bidirectional relationship between seizures and sleep disturbances." (PMID 42023290, 2026). "The findings revealed that alterations in AQP4 polarity closely align with the vascular coverage of pericytes in epilepsy." (PMID 41057266, 2025). "In animal models of epilepsy, AQP4 dysregulation occurs during the early phase of epileptogenesis, which suggest that it is a potential driver of epileptogenesis." (PMID 36244037, 2023). "Nonetheless, these studies collectively indicate that AQP4 can play an important role in the initiation of epilepsy." (PMID 36244037, 2023). "The distribution and expression of aquaporin-4 (AQP4), an astrocytic-specific water channel, is also frequently altered in patients with epilepsy." (PMID 37259148, 2023). "It therefore emerges that AQP4 expression can influence several aspects of CNS; among them, epilepsy also seems to be related to AQP dysfunction, because of the role in water and ion balance." (PMID 37569297, 2023). "Further studies are needed to elucidate the regulatory role of AQP-4 in brain inflammatory processes and to possibly confirm their involvement in the pathogenesis of seizures and epilepsy." (PMID 37569297, 2023). "This subcellular mislocalization significantly impacts neuronal hyperexcitability and understanding how AQP4 becomes dysregulated in epilepsy is beginning to emerge." (PMID 35734218, 2022).
epilepsy (continued). "In brains from individuals with aneurysms, epilepsy, and cancer, astroglial AQP4 density facing the neuropil remained unaltered, as did perivascular AQP4 density." (PMID 36204139, 2022). "A previous study observed a similar reduction in Aqp4 immunoreactivity in the early phase of epilepsy." (PMID 34658792, 2021). "A decrease in Aqp4 has been observed during the latent phase of epilepsy, followed by a significant increase in Aqp4 protein levels 30 days pose SE." (PMID 34658792, 2021). "Although previous studies have examined the regulatory mechanisms of AQP4 levels, most of the studies investigated these mechanisms under pathological conditions such as inflammatory responses, hepatic encephalopathy, epilepsy, brain edema and glioblastoma." (PMID 34006980, 2021). "The dysregulation of Aqp4 carries over to the chronic phase of epilepsy, however, the pathological mechanisms in both phases of epilepsy remain to be further elucidated." (PMID 34658792, 2021). "In vivo models of acute epilepsy with AQP4−/− mice showed elevated seizure thresholds, which can be explained by the increase in extracellular space volume from impaired water uptake." (PMID 33324329, 2020). "Taken together, these data suggest a that dysregulation of AQP4 plays an important role in epilepsy pathology." (PMID 33324329, 2020). "The AQP4 immunogold labeling pattern was similar in human tissue resected from subjects with epilepsy, aneurysm and tumor." (PMID 28317216, 2017). "In the intrahippocampal kainic acid (IHKA) model of epilepsy, AQP4 and GLT1 exhibit different regulation patterns." (PMID 28078912, 2017). "For example, an extensive decrease in the abundance of AQP4 channels in the plasma membrane was detected in the perivascular plasma membrane of astrocytes in the hippocampal area of patients with epilepsy." (PMID 27420057, 2016). "Taken together, an extensive decrease of AQP4 expression in epilepsy patients likely results in perturbed water and ion homeostasis, leading to an increased propensity for seizures and cognitive decline." (PMID 27420057, 2016). "They demonstrated that AQP4 mislocalization precedes the chronic phase of epilepsy, suggesting that astrocytic dysfunction is of pathophysiological relevance." (PMID 24609207, 2015). "Changes in AQP4 polarity during epilepsy were also correlated with laminin expression." (PMID 41057266, 2025). "Both AQP4 dysfunction and α-synuclein elevation may contribute to the pathogenesis of other common disturbances, such as epilepsy and diabetes mellitus." (PMID 38338949, 2024). "A redistribution of AQP4 away from astrocytic endfeet has been reported after severe adult TBI and in animals developing post-TBI epilepsy which contrasts to the increased level of expression of AQP4 on astrocyte endfeet in contact with blood vessels in the hippocampus in our jmTBI model." (PMID 36859364, 2023). "A putative role in the multifactorial genesis of GB-related epilepsy may be sought in dysregulation of AQP4." (PMID 37569297, 2023). "A decrease in dystophin and mislocalization of AQP4 were found in patients with epilepsy." (PMID 36769234, 2023). "However, other actors besides AQPs seem to play key roles in the pathogenesis of epilepsy, from the anchoring system of AQP4 itself to the phosphorylation state of some protein components to genetic and post-transcriptional regulatory mechanisms." (PMID 37569297, 2023). "Finally, studies on post-traumatic epilepsy using an AQP4 knock-out mice model showed that AQP4 seems to play a protective role in post-traumatic seizures by promoting astrogliosis, forming a glial scar, and preventing microgliosis." (PMID 37569297, 2023). "In this review, we evaluate the role of AQP4 dysregulation and mislocalization in epilepsy." (PMID 35734218, 2022).
epilepsy (continued). "In epilepsy models, expression studies of key astrocytic proteins such as aquaporin-4 and inwardly rectifying potassium channel Kir4.1, that are suspected to be epileptogenic, revealed reduction in their immunoreactivity, specifically in cortical (and not hippocampus) astrocytic processes." (PMID 29634780, 2018). "Similarly, astrocytic Cx43 and AQP4 have been shown to be upregulated in epilepsy, exacerbating seizures." (PMID 29520011, 2018). "The fact that AQP4 polarization was similar in all human subjects and independent of the cause of neurosurgical intervention (epilepsy, tumor, aneurism), argue for that the tissue specimens analyzed were representative for the healthy human brain." (PMID 28317216, 2017). "On the other hand, AQP4 is a key molecule to maintain CNS homeostasis, specifically by keeping control of the CNS water content, and its alteration has been observed in numerous brain diseases including epilepsy." (PMID 29182533, 2017). "Altered ECS dynamics may explain the different disease courses seen in AQP4−/− mice, such as in models of edema and epilepsy." (PMID 28078912, 2017). "A further indication for the involvement of AQP4 in epilepsy and for the proposed interplay between AQP4 and Kir4.1 comes from genetic studies showing that several SNPs in the KCNJ10 and AQP4 genes are associated with mTLE (Heuser and others 2010) (see also below)." (PMID 24609207, 2015). "Hence, targeting AQP4 may represent a viable approach for treating neurocognitive dysfunction arising from epilepsy." (PMID 40384856, 2025). "On the hypothesis that the AQP4 expression could regulate the proinflammatory activity in the brain related to the pathogenesis of epilepsy, some studies suggest that the status of chronic and persistent brain inflammation participates in epileptogenesis or reinforces seizures." (PMID 37569297, 2023). "Therefore, astrocytic AQP4 and Kir4.1 channel may be potential targets for a novel treatment for epilepsy." (PMID 31798512, 2019). "Similarly, AQP4−/− mice had a higher seizure threshold but prolonged seizure duration and increased number of seizures in models of epilepsy." (PMID 28078912, 2017). "This could potentially influence our results as certain types of epilepsy affect AQP4 polarization." (PMID 28317216, 2017). "Previous studies have mainly investigated the effects of factors involving inflammation, sleep issues, AQP4 abnormalities, glutamate excess, and glutamate receptor hyperactivation after epilepsy." (PMID 40567884, 2025). "Astrocytes play a crucial role in the pathogenesis of epilepsy modulating the expression of glutamate transporters 1 (GLT1) and AQP4." (PMID 37569297, 2023). "Marked changes in expression of the astrocyte membrane channels aquaporin-4 (AQP4) have been involved in human and animal studies of epilepsy and traumatic brain injury." (PMID 31798512, 2019). "- The overall conclusion that AQP4 polarity plays a crucial role in epilepsy development is not sufficient supported by the data to be included as a key conclusion." (PMID 41057266, 2025). "Studies evaluating AQP4 expression in both the frontal cortex and the hippocampus on a mice model with post-traumatic epilepsy demonstrated that AQP4 levels were higher than in mice that did not develop post-traumatic epilepsy." (PMID 37569297, 2023). "According to previous reports, MiR-28 could up-regulate AQP4 (AQP4) by inhibiting aldehyde dehydrogenase 2 (ALDH2) and promote the recovery of water homeostasis after epilepsy." (PMID 37133759, 2023). "Mechanistically, lack of AQP4 may contribute to the pathophysiology of epilepsy due to the role of water channels in regulating ECS volume and osmolarity, as well as its involvement in K+ homeostasis." (PMID 36244037, 2023).
glioblastoma (57 papers, 2012 to 2026). The most malignant astrocytic tumor (WHO grade IV). "Beyond water transport, AQP4 contributes to cellular dynamics and to the immune architecture of glioblastoma; higher AQP4 expression is associated with M2-like tumor-associated macrophage (TAM) enrichment and immune evasion." (PMID 41324079, 2025). "Glioblastoma (GBM) progression is linked to aquaporin-4 (AQP4), whose functions extend beyond water transport to influence perivascular architecture, immune modulation, edema, and treatment response." (PMID 41324079, 2025). "In glioblastomas and other brain tumors, AQP4 has been linked to increased edema, tumor cell migration, and invasion." (PMID 40575267, 2025). "Nonetheless, AQP4 was also identified as an anti-death target for glioblastoma treatment, as indicated by the discovery that siRNA-facilitated AQP4 repression caused brain tumour cell death." (PMID 38336645, 2024). "Peritumoral edema is linked with AQP4 expression, and AQP4 is significantly increased and redistributed over the borders of tumor cells in glioblastoma." (PMID 37370872, 2023). "Agrin is necessary for polarized distribution, and its reduction causes the redistribution of AQP4 in human glioblastoma." (PMID 36672558, 2022). "In glioblastomas and astrocytomas, AQP4 is upregulated and redistributed, showing a loss of polarized distribution in the end-feet of high grade tumors." (PMID 32111087, 2020). "Exposure to bradykinin for 12 and 24 h respectively caused significant 2.1- and 2.3-fold induction of AQP4 mRNA expression in human malignant glioblastoma cells." (PMID 32182968, 2020). "We confirmed an AQP4 loss in primary human glioblastoma cell cultures after a few passages." (PMID 22590566, 2012). "Furthermore, in glioblastoma, agrin is degraded by MMPs which causes a dramatic effect on the distribution of aquaporin-4 (AQP4)." (PMID 22984437, 2012). "Thus, the speculation that AQP4-specific antibody linked with toxin can be used to selectively damage AQP4-expressing glioblastoma cells has been proposed." (PMID 25886458, 2015). "As explained, the glymphatic system and its role in glioblastoma are largely modulated by fluid dynamics and by AQP4." (PMID 41596575, 2026). "Search terms included combinations of “glioblastoma”, “glymphatic system”, “interstitial fluid flow”, “aquaporin-4”, “blood–brain barrier”, “meningeal lymphatics”, “drug delivery”, “focused ultrasound”, “nanoparticle”, and “immunotherapy”." (PMID 41596575, 2026). "A particularly intriguing case highlighted the coexistence of NMOSD and glioblastoma, where the brain tumor emerged while the patient was undergoing AQP4 immunosuppressive treatment for NMOSD." (PMID 41324079, 2025). "In glioblastoma, AQP4 is often mislocalized or overexpressed within tumor cells, resulting in loss of perivascular polarization and impaired coordination of perivascular flow." (PMID 41324079, 2025). "Although this does not undermine the immunological relevance of AQP4, it introduces nuance into the role of recomanti-AQP4 antibodies in potential therapeutic implications for glioblastoma." (PMID 41324079, 2025). "In brain tumors such as astrocytoma, glioblastoma, and meningioma, the AQP4 expression is upregulated and participates in the pathogenesis of peritumoral edema and the increases of intracranial pressure." (PMID 39043897, 2024). "In glioblastoma, siRNA-mediated down-regulation of AQP4 induced cell apoptosis, suggesting the role of AQP4 in tumor viability." (PMID 39043897, 2024). "Similar results were reported in glioblastoma multiforme, the increases in AQP4 expression corroborated with the peritumoral edema evaluated by magnetic resonance imaging (MRI)." (PMID 39043897, 2024). "In the present study, we demonstrate that the expression and localization of plectin in brain tumors correlate with those of AQP4 and that the abundance of plectin on the extracellular leaflet of the plasmalemma is increased in glioblastoma cells." (PMID 38263015, 2024).
glioblastoma (continued). "In glioblastoma samples, we examined cell status differences and identified that cell status differs according to AQP4 expression levels." (PMID 36599974, 2023). "It is of importance that AQP4 polarity depends on AQP4ex, as demonstrated in AQP4ex-KO mice and in glioblastoma." (PMID 35625560, 2022). "Researchers reported that aquaporin 4 protein was downregulated in glioblastoma cells after chemotherapy and radiotherapy, with reduced peritumoral brain edema." (PMID 35216113, 2022). "Using the TTD database, we discovered that EGFR, ABAT, and PDGFRA are strongly associated with AQP4 expression in the glioblastoma (GBM) classification, and these factors could be the potential AQP4-related immunotherapy targets." (PMID 36523816, 2022). "AQP4 expressing astrocytes, like other cells, are susceptible, to neoplastic change and the most common and malignant glial cancer is glioblastoma multiforme (GBM)." (PMID 34843700, 2022). "Knockdown of AQP4 expression with siRNA resulted in impairment of glioblastoma cell migration and invasion in cell line LN229." (PMID 34769339, 2021). "Fascinatingly, knocking-down AQP4 expression concurrently led to the suppression of migration and invasion of glioblastoma cells." (PMID 32182968, 2020). "The bradykinin-BDKRB1 axis is involved in regulating the aqp4 gene in glioblastoma cells via activating the MAPK-NF-κB mechanism." (PMID 32182968, 2020). "In brain tumors, AQP4 is massively expressed and plays an important role in glioblastoma-related edema." (PMID 32182968, 2020). "Compared to human normal brain tissues, expression of AQP4 mRNA in human glioblastomas was induced 2.9-fold." (PMID 32182968, 2020). "Effects of bradykinin-induced AQP4 expression on the migration and invasion of human malignant glioblastoma cells were evaluated using wound-healing and Matrigel-based invasion assays." (PMID 32182968, 2020). "In comparison, this study provides a whole mechanism regarding bradykinin-induced aqp4 gene expression in glioblastomas via activation of the BDKRB1-MEK4-ERK1/2-NF-κB axis." (PMID 32182968, 2020). "Accordingly, AQP4 participates in maintenance and modulation of activities and functions of glioblastoma cells in brain tumors." (PMID 32182968, 2020). "AQP4 upregulation and redistribution in glioblastoma has been suggested to contribute to tumor-associated edema observed by magnetic resonance imaging, and conversely enhance clearance of excess fluid." (PMID 32679804, 2020). "Our results by immunohistochemistry further reveal that levels of the AQP4 protein in human glioblastomas were elevated compared to human meningioma tissues." (PMID 32182968, 2020). "In conclusion, this study revealed upregulation of AQP4 mRNA and protein expression in human glioblastomas." (PMID 32182968, 2020). "The present study showed overexpression of AQP4 in human glioblastomas and involvement of the bradykinin-BDKRB1 axis in regulating expression of this channel gene." (PMID 32182968, 2020). "Successively, expression of AQP4 mRNA in murine GL-261 glioblastoma cells was induced by 3.2-fold following exposure to bradykinin." (PMID 32182968, 2020). "As a result, the bradykinin-BDKRB1 axis-induced AQP4 plays an important role in the migration and invasion of glioblastoma cells." (PMID 32182968, 2020). "As a result, the bradykinin-BDKRB1/2 axis contributes to regulation of AQP4 expression as well as migration and invasion of glioblastoma cells." (PMID 32182968, 2020). "The protein expression of AQP4 in human glioblastoma is indeed upregulated in comparison with healthy brain tissue." (PMID 33297299, 2020). "In contrast, exposure to 100 nM bradykinin for 24 h elevated amounts of AQP4 in human U87 MG glioblastoma cells (left-bottom panel)." (PMID 32182968, 2020). "Exposure to bradykinin induced AQP4 mRNA expression in human malignant glioblastoma cells by 3.6 fold." (PMID 32182968, 2020).